CGAS (cyclic GMP-AMP synthase)
Diseases named in the same sentence as CGAS in open-access papers (continued):
Sharing a sentence is not in itself a finding about the gene and the disease.
colitis (continued). "On the other hand, it can synergize with N8AS to inhibit the activation of the cGAS STING signaling axis in cells, thereby alleviating colitis." (PMID 41257293, 2025). "cGAS has been demonstrated to be upregulated in the intestinal epithelium of humans with IBD and mice subjected to DSS colitis." (PMID 39050748, 2024). "In our study, SP suppressed the activation of the cGAS-STING pathway in a dose-dependent manner, both in colitis mice and in TNF-α-induced colonic epithelial cells." (PMID 38725846, 2024). "Immunoblot analysis confirmed that the intraperitoneal injection of RU.521 in mice models targeted the cGAS-STING signaling pathway and reduced signs of colitis in mice." (PMID 37566032, 2023). "Intriguingly, activation of cGAS-STING pathway reduced the expression of ANP and its receptor in the intestine of IBD patients and colitis mice." (PMID 37566032, 2023). "Further research found that only 10% of IL-10 and cGAS dual-gene knockout mice formed intestinal polyps, indicating that the cGAS-STING signaling pathway exerts an indispensable role in IL-10 related colitis in mice." (PMID 37781360, 2023). "In the murine model of colitis, GSDMD is activated during intestinal inflammation and is confirmed as a negative regulator controlling cyclic GMP-AMP synthase (cGAS)–dependent inflammation, providing a new clue to restrain colitis by regulating GSDMD." (PMID 35774778, 2022). "Then, it was found that intestinal cGAS-STING pathways were upregulated in UC patients, Crohn’s disease colitis (CD) patients, and DSS-induced colitis mice." (PMID 36467059, 2022). "Given the close relationship between colitis and host immune function, these findings suggest that N8AS may exert protective effects against colitis at least in part by inhibiting the cGAS–STING signaling pathway." (PMID 41257293, 2025). "Given that the NF-κB pathway is downstream of cGAS/STING signaling, we hypothesized that LGG may induce IL-10 expression in a STING/NF-κB-dependent manner in the context of colitis." (PMID 39895628, 2025). "Chemically induced colitis results in destruction of intestinal stem cells and impaired intestinal barrier function in cGAS KO but not STING mutant mice." (PMID 39050748, 2024). "Chemically-induced colitis resulted in destruction of intestinal stem cells and impaired intestinal barrier function in cGAS KO but not STING mutant mice." (PMID 39050748, 2024). "Unlike Sting deficiency, the absence of Cgas worsened colitis and decreased autophagy in the DSS-induced mouse model independent of microbiota, although cGAS inhibitor illustrated benefit in restricting inflammation in DSS-induced colitis mouse model." (PMID 37781354, 2023). "In a colitis model induced by sodium dextran sulfate (DSS) in mice, compared with WT mice, the colitis symptoms of STING mutant and cGAS-/- mice were obviously reduced, and that the expression level of STING protein is increased in colon M1 macrophages of both DSS-treated WT mice and IBD patients." (PMID 37781360, 2023). "Indeed, GSDMD functions in macrophages are a negative regulator of cGAS-STING-dependent inflammation, thereby protecting against colitis." (PMID 37566032, 2023). "Our findings not only demonstrate that SP inhibits the cGAS-STING through the suppression of mtDNA release but also elucidate the capability of SP to directly suppress the STING pathway, thereby alleviating inflammation and ferroptosis in the intestinal epithelium during colitis." (PMID 38725846, 2024). "S16 and S17C), suggesting that Ku70 may not require cGAS-STING–mediated signaling during the development of colitis." (PMID 38277448, 2024). "Based on the activation of the genomic instability-induced cGAS-STING pathway as a contributing factor to colitis, we questioned whether blocking the cGAS-STING pathway in Dhx9ΔIEC mice would partially alleviate the colitis phenotype." (PMID 38594251, 2024).
colitis (continued). "The study proposes a physiological role for non-canonical inflammasome and GSDMD activation, limiting the severity of experimental DSS-colitis models by restricting cGAS-mediated inflammation in macrophages, independent of microbiota-associated changes or the production of antimicrobial peptides." (PMID 35712726, 2022).
ovarian carcinoma (40 papers, 2020 to 2026). A malignant neoplasm originating from the surface ovarian epithelium. "The loss of 53BP1 in ovarian cancer cells enhances cGAS-dependent antitumor immunity by enabling excessive DNA end-resection during double-strand break repair, generating cytoplasmic DNA fragments." (PMID 39949780, 2025). "Dysregulation of the cGAS–STING pathway has been implicated in ovarian cancer, where alterations in DNA repair mechanisms and genomic instability can lead to the accumulation of ssDNA, activating the cGAS–STING pathway." (PMID 39408764, 2024). "In BRCA-deficient ovarian cancer and triple-negative breast cancer mouse models, Olaparib can activate the cGAS/STING pathway in tumor cells, thereby activating TBK1/IRF3 signaling in DCs." (PMID 38111536, 2023). "The effect of SR-717 on HU-arrested forks was also reproduced in the cGAS-deficient ovarian carcinoma cell line SKOV-3." (PMID 36710880, 2022). "For instance, olaparib treatment induced a strong antitumour immune response in different pre-clinical tumour mouse models, including TNBC, SCLC and BRCA1-deficient ovarian cancer, in a cGAS/STING-dependent manner." (PMID 34885119, 2021). "Furthermore, activating the cGAS signaling in cancer-associated fibroblast promotes platinum resistance of ovarian cancer cells." (PMID 40337520, 2025). "In BRCA-deficient ovarian cancer, triple-negative breast cancer, and small cell lung cancer mouse models, Olaparib may activate the cGAS-STING pathway, upregulate CXCL10 and CCL5 expression, recruit CD8+ T cells to tumor tissue, and activate antitumor immune responses." (PMID 38111536, 2023). "Specifically, niraparib has demonstrated synergistic antitumor activity in combination with PD-L1 blockade, primarily by enhancing the immune response by activating the cGAS/STING signaling pathway in ovarian cancer." (PMID 41596347, 2026). "In ovarian cancer cells, CX-5461 induces cytosolic DNA accumulation, activating the cGAS-STING pathway." (PMID 39949780, 2025). "Reducing CENPM expression in ovarian cancer (OC) cells activates the cGAS-STING pathway, suppressing tumor growth and spread by inducing pyroptosis, an inflammatory cell death." (PMID 39949780, 2025). "Mechanistically, SETDB1 knockout in ovarian cancer led to mitotic defects, micronuclei formation, and upregulation of PD‐L1 via the cGAS‐STING pathway." (PMID 39764697, 2025). "The COUPLET study provided valuable insights into the activation of the cGAS-STING pathway in ovarian cancer when treated with a combination of rucaparib and atezolizumab." (PMID 39949780, 2025). "The cGAS-STING signaling pathway was previously reported to be defective in a large portion of ovarian cancer cell lines and tumors." (PMID 39851178, 2025). "Liposomal low-dose cytarabine (Ara-C) offers a promising treatment for ovarian cancer by activating the cGAS-STING pathway, a key component of cancer immunotherapy." (PMID 39949780, 2025). "Cancer-associated fibroblasts (CAFs) promote platinum resistance in ovarian cancer by activating the cGAS-STING pathway after DNA transfer from cisplatin-exposed cancer cells." (PMID 39949780, 2025). "Future functional experiments are needed to elucidate the role of STING in ovarian carcinomas and to assess the integrity of the cGAS-STING pathway, which will help to provide more appropriate therapeutic strategies for different ovarian cancer subtypes." (PMID 39445027, 2024). "Overexpression of SETDB1-TRIM28 was found in several ovarian cancer cell lines, thereby inactivating the cGAS-STING pathway." (PMID 39445027, 2024). "Consistent with this, in ovarian cancer cells, we verified that relocalization of nuclear cGAS suppressed HR activity after combinational treatment, while cGAS knockdown partially compromised DNA damage." (PMID 39247812, 2024). "Whereas, further studies are still needed to clarify the expression levels of cGAS/STING in ovarian cancer tissues." (PMID 39445027, 2024).
ovarian carcinoma (continued). "PARPi further interferes with CD8+ T cell maturation despite upregulating the cGAS/STING pathway which was found to be defective in ovarian cancer." (PMID 38542143, 2024). "The cGAS/STING pathway has been assigned a critical role for cisplatin- induced PD-L1 in ovarian cancer." (PMID 37138100, 2023). "Breast and ovarian cancers harboring BRCA mutations have been shown to harbor high levels of micronuclei and cGas/STING activity." (PMID 35082152, 2022). "Further studies will be necessary to explore the effect of targeting the cGAS/STING pathway in ovarian cancers and the effect of PARP inhibitors or ICBs." (PMID 34620163, 2021). "The current study shows for the first time that CX-5461 treatment in ovarian cancer cells induces the release of cytoplasmic DNA that stimulates cGAS–STING signaling, leading to the production of IFN type I in both cancer cells and xenografts in vivo." (PMID 34680204, 2021). "To examine the relevance of the HMGB2-TOP1cc-cGAS pathway in immune checkpoint blockade treatment, we utilized an immune competent syngeneic ovarian cancer ID8-Defb29/Vegf-a mouse model." (PMID 32075966, 2020). "In pre-clinical models of ovarian cancers, cisplatin elicits anti-tumour immune responses through activation of the cGAS/STING pathway." (PMID 32200422, 2020). "In ovarian cancer, GRB2 maintains replication fork stability by inhibiting RAD51 ATPase activity, preventing cytosolic DNA release that activates cGAS‐STING; GRB2 deficiency allows PARP inhibitors (PARPis) to induce DNA fragment release and enhance antitumour immunity." (PMID 41350246, 2025). "Furthermore, the phosphorylation levels of TBK1, P65, and IRF3 were significantly elevated in ovarian cancer cells and normal immortalized ovarian epithelial cells treated by both PARPi and Entinostat, indicating the activation of cGAS-STING pathway." (PMID 37063431, 2023). "It was found that a majority of human ovarian cancer cells lack either cGAS, STING, or both." (PMID 32774773, 2020). "However, cGAS-STING is reported to be defective in a large portion of HGSC, and there have been limited efforts to evaluate the immune response to PARPis in cGAS-STING–deficient models of ovarian cancer." (PMID 39851178, 2025). "In addition, in pancreatic tumors, ovarian cancer, and nasopharyngeal carcinoma, blocking the ubiquitination of the cGAS-STING pathway may represent a novel therapeutic approach to inhibit anti-tumor immunity." (PMID 40028324, 2025). "In ovarian cancer cells, IL-19 expression is activated by the JNK and cGAS-STING pathways in response to DNA damage, driving cytokine production." (PMID 39949780, 2025). "In ovarian cancer, WEE1 inhibition combined with ATR inhibitors (ATRi) increases DNA damage and stress, triggering cytoplasmic dsDNA accumulation and activating the cGAS-STING pathway." (PMID 39949780, 2025). "Alone, Niraparib increases PD-L1 expression in ovarian cancer cells and enhances CD8+ T cell recruitment, activating an immune response via cGAS-STING, but is limited by immunosuppressive feedback from PD-L1." (PMID 39949780, 2025). "Treatment with different ATRi results in innate immune and T cell activation mediated by cGAS-STING pathway in various mouse models of cancer, including those for prostate cancer, hepatocellular carcinoma and ovarian cancer." (PMID 34885119, 2021). "We first selected 3 SLFN11-deficient (EFO-21, KURAMOCHI, RMGI, SLFN11–) and 3 SLFN11-proficient (OAW42, OV7 and OV-56, SLFN11+) ovarian cancer cell lines that were all STING pathway proficient, as illustrated by cGAS and IRF3 expression." (PMID 34549724, 2021). "Indeed, reduced cGAS and STING expression are associated with poorer survival of patients with lung adenocarcinoma and invasive breast ductal carcinoma; albeit, there is no discernible association among patients with lung squamous cell carcinoma or ovarian cancer." (PMID 32774773, 2020).
ovarian carcinoma (continued). "This work highlights how different PARPis, especially talazoparib, modulate immune-related gene expression in ovarian cancer cells, independent of the cGAS-STING pathway." (PMID 39851178, 2025). "However, many ovarian cancer cells exhibit impaired STING signaling, often due to epigenetic silencing, such as DNA hypermethylation of STING or its activator cGAS." (PMID 39949780, 2025). "Similarly, in ovarian cancer, the SETDB1-TRIM28 complex represses the expression of PD-L1 and the infiltration of CD8+ T cells and inhibits antitumour immunity by regulating the cGAS-STING pathway." (PMID 38317200, 2024). "Further highlighting the potential importance of RIGI and MDA5 in ovarian cancer, de Queiroz found that cGAS-STING activation, but not that of MDA5 or RIGI, was impaired in a majority of ovarian cancer cell lines." (PMID 39159817, 2024). "In syngeneic ovarian cancer (ID8) and colon cancer (CT26) mice models, poly (ADP-ribose) polymerase inhibitors (PARPi) promoted the levels of phosphorylated Irf3 and STING, which implies active cGAS-STING signaling pathway in vivo." (PMID 32887628, 2020).
hepatocellular carcinoma (39 papers, 2017 to 2026). A malignant tumor that arises from hepatocytes. "Numerous liver diseases, such as viral hepatitis, non-alcoholic fatty liver disease, alcoholic liver disease, primary hepatocellular carcinoma, and hepatic ischemia–reperfusion damage, have been linked to the crucial function of cGAS-STING signaling." (PMID 37370115, 2023). "Our research found that cucurbitacin B (CuB), a natural component derived from traditional Chinese medicine, had significant anti-hepatocellular carcinoma properties and exerted anti-tumor effects through the cGAS-STING pathway." (PMID 41751402, 2026). "BACKGROUND: Cabozantinib, a tyrosine kinase inhibitor (TKI) approved for advanced hepatocellular carcinoma (HCC), has established clinical benefit although the underlying immunomodulatory mechanisms, particularly those involving mitochondrial stress and the cGAS/STING pathway, remain poorly defined." (PMID 41508119, 2026). "For instance, RT upregulates PD-L1 expression in hepatocellular carcinoma (HCC) via the cGAS-STING pathway, leading to immune cloaking and reduced Cytotoxic T lymphocyte (CTL) activity." (PMID 39742149, 2025). "IDI1, a metabolic enzyme, interacts with cGAS, and TRIM41, an E3 ligase from hepatocellular carcinoma cells, promotes cGAS degradation, suggesting a role in innate immunity and a potential target for liver cancer treatment." (PMID 40028324, 2025). "Lower cGAS or STING expression in cancer samples was correlated to worse patient outcomes with hepatocellular carcinoma and lung adenocarcinoma, suggesting the importance of functional cGAS-STING axis activity in proper tumor suppression." (PMID 40552295, 2025). "In hepatocellular carcinoma, activation of the cGAS-STING pathway has been shown to upregulate PD-L1 expression via the STING-TBK1-IRF3 axis, promoting immune evasion." (PMID 40051782, 2025). "For instance, the abrogation of BRCA1-PALB2 interaction in hepatocellular carcinoma (HCC) cells potently induced mtDNA leakage into the cytoplasm to be sensed by cGAS." (PMID 38630271, 2024). "cGAS is a major factor in promoting hepatocellular carcinoma cell (HCC) tumor growth by suppressing ferroptosis in vivo." (PMID 37834184, 2023). "Moreover, the cGAS-STING signaling pathway was also closely associated with tumor immunity in hepatocellular carcinoma (HCC)." (PMID 34483930, 2021). "Intracellular zinc ions could produce reactive oxygen species, facilitated by the generated H2S gas from ZnS@BSA via specifically inhibiting catalase in hepatocellular carcinoma cells through activating the cGAS/STING signals in mice." (PMID 40375976, 2025). "Furthermore, through activation of signaling pathways such as LPS/TLR4, cGAS/STING, and TGF-β, BEVs promote the progression of metabolism-associated fatty liver disease (MAFLD), liver fibrosis, and hepatocellular carcinoma." (PMID 40621163, 2025). "The activation of the cGAS-STING pathway has received attention for its prognostic value in gastric cancer and hepatocellular carcinoma, it is unknown whether cGAS-STING may also be potential prognostic value in BRCA." (PMID 37051596, 2023). "However, HBV-derived dsDNA can also induce the innate immune response by expressing high levels of cGAS in human hepatoma Li23 cells." (PMID 33995425, 2021). "To test this hypothesis, we first reconstituted a functional cGAS-STING pathway in human hepatoma (HepG2) cells by expressing human cGAS and STING." (PMID 33870849, 2021). "For instance, in diabetic hepatocellular carcinoma (HCC), a cancer prone to metastasize, neutrophils invade the tumor and produce NETs, which then activate cGAS in HCC cells." (PMID 37187738, 2023). "Whether this is due to the deficiency of cyclic GMP-AMP synthase (cGAS)- stimulator of interferon genes (STING) pathway in hepatocytes and hepatoma cells or efficient digestion of the released viral DNA by cytoplasmic nucleases is currently under investigation." (PMID 28945802, 2017).
hepatocellular carcinoma (continued). "Apart from CRC, gut microbiome dysbiosis characterized by elevated levels of Streptococcus also reduces the efficacy of RT in hepatocellular carcinoma (HCC) by impairing antigen presentation and T cell activities via the cGAS/STING/IFN‐I signalling cascade." (PMID 41028942, 2025). "The released Zn2+ activated cGAS/STING signaling, whereas S2− formed H2S gas that inhibited catalase and cooperated with zinc ions to generate ROS in hepatocellular carcinoma (HCC) cells." (PMID 37514189, 2023). "Indeed, the cGAS-STING pathway displays a multifaceted, Janus-faced influence on hepatocellular carcinoma (HCC) pathogenesis." (PMID 40098962, 2025). "Moreover, although cGAS-STING signalling affects liver injury, hepatocellular carcinoma (HCC), non-alcoholic fatty liver disease (NAFLD) and viral hepatitis, the detailed mechanism of cGAS-STING signalling in liver inflammation remains unexplored." (PMID 39183465, 2024). "Indeed, activation of cGAS or STING with pharmaceutical treatment induced IFN response and inhibited viral replication in HBV-infected human hepatoma cells and immortalized mouse hepatocytes." (PMID 33995425, 2021). "It has been shown that cGAS participates in regulating ferroptosis and promoting the development of hepatocellular carcinoma (HCC), independent of the classical cGAS-STING signaling pathway." (PMID 38808552, 2024). "In hepatocellular carcinoma (HCC) cells, it has been demonstrated that the cGAS-STING pathway is not involved in regulating the mitochondrial fission regulator DRP1." (PMID 37548939, 2024). "Herein, a previously unexplored mechanism is revealed linking DNA repair, the cGAS‐STING pathway, the tumor microenvironment, and radiotherapy sensitivity, and offer an attractive novel target for HCC radiotherapy, which may be beneficial to patients with hepatocellular carcinoma." (PMID 38381090, 2024). "However, the prognostic value and correlations with immune infiltrates of the cGAS-STING pathway in hepatocellular carcinoma (HCC) have not been clarified." (PMID 33006365, 2020).